HLTF (helicase like transcription factor)
Diseases named in the same sentence as HLTF in open-access papers (continued):
Sharing a sentence is not in itself a finding about the gene and the disease.
thyroid cancer (3 papers, 2014 to 2021). "In head and neck, cervix and thyroid cancers, the expression of HLTF truncated protein has been associated with poor outcome." (PMID 29661164, 2018). "Finally, we know that HLTF is implicated in post-replication DNA repair, a mechanism that could be disturbed in thyroid cancer cells." (PMID 25005870, 2014). "To better understand the role of HLTF in thyroid cancer progression, we would like to study HLTF expression profiles, both at the mRNA level (by RT-PCR) to identify potential mutations and at the protein level." (PMID 25005870, 2014). "Using immunocytochemistry on several thyroid cancer cell lines, we visualized the HLTF protein exclusively in the nucleus." (PMID 25005870, 2014). "The purpose of the study is to examine the level of expression of the helicase-like transcription factor (HLTF) in relation to neoplastic progression of thyroid carcinomas." (PMID 25005870, 2014). "Finally, the HLTF protein expression was investigated by Western blotting in four thyroid cancer cell lines." (PMID 25005870, 2014). "The 115-kDa full size HLTF protein was immunodetected in four studied thyroid cancer cell lines." (PMID 25005870, 2014). "Three truncated HLTF forms lacking the domains that are involved in DNA repair were detected in thyroid carcinomas, strengthening the role of HLTF as a tumor suppressor." (PMID 25005870, 2014). "In the immunoblotting experiments presented here, we could not discriminate one type of thyroid cancer from another because all of the cell lines shared the same expression profile of HLTF protein forms." (PMID 25005870, 2014).
colon adenoma (2 papers, 2006 to 2012). An adenoma that arises from the colon. "We have provided direct genetic evidence that loss of HLTF function promotes the malignant transformation of intestinal or colonic adenomas to carcinomas." (PMID 22452792, 2012). "Taken together, our results demonstrate that loss of HLTF function promotes the malignant transformation of intestinal or colonic adenomas to carcinomas by inducing genomic instability." (PMID 22452792, 2012). "In this line of reasoning, during tumor progression, tumor cells might circumvent the antiproliferative effect of HLTF gene by hypermethylation, as observed in advanced colon adenomas." (PMID 16762066, 2006).
colorectal tumors (2 papers, 2006 to 2019). "One could hypothesize that sequestration of HLTF outside of the nucleus might be part of the transformed phenotype for p27Kip, a negative regulator of the cell cycle that accumulates in the cytoplasm of colorectal tumors." (PMID 16762066, 2006).
Fanconi Anaemia (2 papers, 2024 to 2026). "HLTF expression was found to be significantly elevated in PV and down-regulated in multiple anemia-related disorders, including MDS, acute myeloid leukemia (AML), Fanconi anemia (FA), and chronic kidney disease (CKD)." (PMID 41521666, 2026). "Surprisingly, guides targeting the fork reversal factors (SMARCAL1, HLTF, ZRANB3, SHPRH) or components of the Fanconi Anaemia pathway were neither enriched nor depleted, despite previous studies suggesting a genetic interaction between some of these factors and PRIMPOL in transformed cell lines." (PMID 37971291, 2024).
hypopharyngeal squamous cell carcinoma (2 papers, 2014 to 2023). "In invasive hypopharyngeal squamous-cell carcinomas, we also showed that truncated HLTF protein variants increase during tumor progression when comparing carcinomas to normal epithelia or dysplasia and that HLTF overexpression was associated with a worse prognosis." (PMID 25005870, 2014). "Moreover, high levels of HLTF expression were found to be associated with rapid recurrence rates in a series of 100 hypopharyngeal squamous cell carcinomas (SCC)." (PMID 25005870, 2014).
kidney tumors (2 papers, 2006 to 2018). "In the present study, two rabbit antisera raised against individual HLTF protein variants were used for immunocytochemical analyses of DES-induced kidney tumors at various stages of development, and demonstrated HLTF over-expression as an early event." (PMID 16762066, 2006). "On the other hand, high levels of HLTF protein expression were observed in early stages of an experimental model of estrogen induced kidney tumors, linking HLTF to the initial steps of carcinogenesis." (PMID 30586904, 2018). "HLTF expression was conserved in the HKT-1097 cell line established from kidney tumors, but again only 10% of positive cells were found in xenografts produced by HKT-1097 cells in nude mice." (PMID 16762066, 2006). "In the present study, we have detected HLTF protein expression at early stages of development of renal tumors induced by DES in Syrian golden hamsters." (PMID 16762066, 2006). "In contrast, in the kidney tumors fixed in alcoholic Bouin's mixture, most HLTF-positive cells presented a strong cytoplasmic signal, while only few cells displayed a nuclear staining." (PMID 16762066, 2006). "According to this model, if HLTF is only expressed by these cancer stem cells and their direct progeny, positive cells should appear randomly distributed within kidney tumors." (PMID 16762066, 2006). "In the present study, we investigated HLTF expression by immunohistochemistry in a model of kidney tumors induced by continuous administration of diethylstilbestrol to male Syrian golden hamsters." (PMID 16762066, 2006). "An explanation might be found in the HLTF expression pattern that we observed here during kidney tumor progression: although every single cell stained for HLTF in tumor buds, the HLTF signal was only detected in about 10% of cells scattered in larger tumors." (PMID 16762066, 2006).
lung carcinoma (2 papers, 2010 to 2018). "In lung cancer, one study assessed the hypermethylation of HLTF in a cohort of 54 patients with NSCLC." (PMID 29661164, 2018). "We analyzed online databases (TCGA, COSMIC) for HLTF alterations in NSCLC and assessed WT and spliced HLTF mRNAs expression by RT-ddPCR in 39 lung cancer cell lines and 171 patients with resected stage I-II NSCLC." (PMID 29661164, 2018). "Importantly, our study identified seven novel methylated candidates in lung cancer, including HLTF, ID4, BNIP3, H2AFX, CACNA1G, CACNA1A and TGIF." (PMID 20849603, 2010). "MS-MLPA allowed identification of a number of new and possibly interesting epigenetic alterations such as HLTF, ID4, BNIP3, H2AFX, CACNA1G, CACNA1A and TGIF genes, serving to gain more insight into the development of lung carcinomas." (PMID 20849603, 2010). "So far, to our knowledge, there are no published data about the expression of HLTF (wild-type and its truncated forms) in lung cancer." (PMID 29661164, 2018).
metastatic disease (2 papers, 2014 to 2021). "HLTF methylation in the serum was significantly correlated with metastatic diseases (p = 0.013) and advanced tumor stages (p = 0.0489) as well as T4 tumors (T1-3 vs. T4, p = 0.046)." (PMID 24708595, 2014). "Methylated HLTF DNA in serum is significantly correlated with tumor size, more aggressive tumors, advanced stage (III or IV) metastatic disease, including micro-metastasis, and shorter survival." (PMID 34010296, 2021).
myelodysplastic syndrome (2 papers, 2023 to 2026). A clonal hematopoietic disorder characterized by dysplasia and ineffective hematopoiesis in one or more of the hematopoietic cell lines. "In erythroid disorders, HLTF is up-regulated in polycythemia vera (PV) and down-regulated in myelodysplastic syndromes (MDS)." (PMID 41521666, 2026).
uterine cancer (2 papers, 2014 to 2018). Primary or metastatic malignant neoplasm involving the uterine corpus and/or the cervix. "Several studies revealed reduced expression of HLTF caused by promoter hypermethylation in colon, esophageal, gastric, and uterine cancers, suggesting that HLTF silencing conferred a selective growth advantage." (PMID 30586904, 2018). "Several studies have demonstrated that the HLTF promoter is hypermethylated in human colorectal, gastric, esophageal and uterine cancers, suggesting that HLTF silencing may play a crucial role in cancer." (PMID 25005870, 2014).
virus infection (2 papers, 2018 to 2020). "At low MOI, knockdown of HLTF significantly increased the efficiency of virus infection in two independent HFFF-TERT lines stably transduced with different HLTF shRNA constructs." (PMID 30122656, 2018). "HIV-1 Vpr and its Vpr/Vpx homologs in HIV-2 and SIV associate with the cullin4A-DDB1-DCAF1 complex to target multiple host factors including tet methylcytosine dioxygenase 2 (TET2) and helicase-like transcription factor (HLTF) for degradation, thus promoting virus infection." (PMID 31968566, 2020). "This suggested that HLTF might play a key functional role in early viral infection, possibly being degraded by the virus to evade antiviral restriction." (PMID 30122656, 2018).
anaplastic carcinomas (1 paper, 2014). "In contrast, in papillary carcinomas, the HLTF staining was limited to the cytoplasm, whereas follicular and anaplastic carcinomas exhibited weak cytoplasmic and nuclear immunostaining (respectively)." (PMID 25005870, 2014). "We also studied the expression of HLTF protein by immunocytofluorescence in 3 different transformed thyroid cell lines, B-CPAP, FTC-133 and 8505C, derived from human papillary carcinoma, follicular carcinoma and anaplastic carcinoma, respectively." (PMID 25005870, 2014).
anemia (1 paper, 2026). A reduction in the number of red blood cells, the amount of hemoglobin, and/or the volume of packed red blood cells. "These phenotypes were further validated in vivo using BMT models, where HLTF knockdown resulted in anemia, reduced erythroid output, and compensatory splenic hematopoiesis." (PMID 41521666, 2026). "Loss of HLTF leads to reduced GATA1 expression, impaired RBC maturation, anemia, and compensatory extramedullary hematopoiesis." (PMID 41521666, 2026).
bladder cancer (1 paper, 2020). "Similar results were also found in HLTF-KO and PARP1-KO HONE6 and bladder cancer T24 cells." (PMID 33281189, 2020).
Cirrhosis (1 paper, 2023). A chronic disorder of the liver in which liver tissue becomes scarred and is partially replaced by regenerative nodules and fibrotic tissue resulting in loss of liver function. "In the same manner, associated with cirrhosis risk rs11119982 (ATF3) C allele creates one unique TFBS for the helicase-like transcription factor (HLTF) which is involved with altering chromatin structure." (PMID 37059745, 2023).
colon adenocarcinoma (1 paper, 2019). "Methylation of the ESR1, MGMT, HPP1/TPEF, HLTF, and NGFR genes is associated with the onset of colon adenocarcinoma and occurs during the early stages of oncogenesis." (PMID 31852837, 2019).
endothelial dysfunction (1 paper, 2025). In vascular diseases, endothelial dysfunction is a systemic pathological state of the endothelium (the inner lining of blood vessels) and can be broadly defined as an imbalance between vasodilating and vasoconstricting substances produced by (or acting on) the endothelium. "Furthermore, wound-healing assays revealed that the protective effects of UBE2N OE on sunitinib-induced endothelial dysfunction were reversed by inhibition of RNF8 or RNF168 but not HLTF and SHPRH." (PMID 39895626, 2025).
follicular adenomas (1 paper, 2014). "In this context, we propose further testing of HLTF as a new potential marker of follicular adenomas on FNA using a threshold of 30% HLTF-positive nuclei." (PMID 25005870, 2014). "Using quantitative analysis, we demonstrated that HLTF expression decreased significantly when comparing follicular adenomas to follicular carcinomas." (PMID 25005870, 2014). "However, our results are preliminary, and HLTF expression should be studied in a larger series of follicular adenomas versus carcinomas." (PMID 25005870, 2014).
glioma (1 paper, 2024). A benign or malignant brain and spinal cord tumor that arises from glial cells (astrocytes, oligodendrocytes, ependymal cells). "We also show that higher DTX2 levels are associated with lower HLTF expression in glioma." (PMID 38163902, 2024). "Western blotting revealed that protein levels of HLTF in glioma cells were greatly reduced after overexpression of DTX2 but was highly increased after DTX2 knockdown, indicating the negative regulation of DTX2 and HLTF." (PMID 38163902, 2024). "Our results showed that knockdown of HLTF stimulated cell proliferation in shHLTF#1 and shHLTF#2 glioma cells." (PMID 38163902, 2024). "Here, we investigated the subcellular location of DTX2 and HLTF in glioma cells was by immunofluorescence assay." (PMID 38163902, 2024). "The limitation of this study is that the HLTF expression and prognostic value in glioma samples also need further investigating." (PMID 38163902, 2024). "In contrast to the results for HLTF-knockdown cells, HLTF-overexpressing U87 and U251 glioma cells showed lower cell viability, formed fewer expression colonies, and had decreased migration ability compared with controls." (PMID 38163902, 2024). "All those results suggest that DTX2 suppresses glioma cell proliferation, migration, and invasion through HLTF." (PMID 38163902, 2024). "Our results also showed that ectopic expression of HLTF decreased cell growth and invasion of glioma cells, whereas silencing of HLTF induced glioma cell growth and metastasis." (PMID 38163902, 2024). "The newly identified DTX2/HLTF axis strengthens the potential oncogenic role of DTX2 and tumor suppressor role of HLTF in glioma and provides potential therapeutic markers for glioma." (PMID 38163902, 2024). "Collectively, the results of this study demonstrated the involvement of the DTX2/HLTF axis in glioma cell progression and tumor growth." (PMID 38163902, 2024). "In vitro ubiquitination assays showed increased HLTF ubiquitination in DTX2 overexpressed glioma cells and decreased HLTF ubiquitination in DTX2 knockdown cells, which confirmed our assumptions." (PMID 38163902, 2024). "To investigate the effects of HLTF on glioma, we silenced HLTF in two glioma cell lines (U87 and U251) by RNA interference using two shRNAs (shHLTF#1 and shHLTF#2)." (PMID 38163902, 2024). "All these findings suggest that the DTX2/HLTF axis is crucial for glioma progression and may represent a promising target for the treatment of glioma." (PMID 38163902, 2024). "As E3 ubiquitin-protein ligase is likely to be involved in the regulation of protein expression, we evaluated whether DTX2 regulated the stability of HLTF protein in glioma cells." (PMID 38163902, 2024). "We have identified DTX2/HLTF as a new axis in the development of glioma that could serve as a prognostic or therapeutic marker." (PMID 38163902, 2024). "Having shown that DTX2 promoted the development of glioma and negatively regulated the expression of HLTF in vitro, we next investigated whether such regulation had an effect on in vivo tumor growth in nude mice models." (PMID 38163902, 2024). "All of those results indicate that DTX2 binds to HLTF in glioma." (PMID 38163902, 2024). "Furthermore, we detected DTX2 and HLTF expression levels in glioma tissues by IHC and found that HLTF expression was negatively associated with DTX2 expression in 180 glioma tissues." (PMID 38163902, 2024). "Finally, tumor xenograft experiments further verified the involvement of the DTX2/HLTF axis in tumor growth in glioma." (PMID 38163902, 2024). "We also observed that HLTF inhibited proliferation and migration of glioma cells." (PMID 38163902, 2024). "Furthermore, we found that HLTF could bind to DTX2 in glioma cells, and that the two proteins were co-located in the nucleus." (PMID 38163902, 2024). "To investigate whether the effects of DTX2 on glioma depended on HLTF, we performed double knockdown of DTX2 and HLTF (shDTX2#1 + shHLTF#1) in U87 and U251 cells." (PMID 38163902, 2024).
glioma (continued). "The results showed upregulation of HLTF expression in glioma cells with DTX2 knockdown and downregulation in the DTX2-overexpressing U87 and U251 cells, indicating a negative regulation between DTX2 and HLTF." (PMID 38163902, 2024).
head and neck squamous cell carcinoma (1 paper, 2014). A squamous cell carcinoma that arises from any of the following anatomic sites: lip and oral cavity, nasal cavity, paranasal sinuses, pharynx, larynx, and salivary glands. "Recently, we studied the immunohistochemical expression of HLTF in relation to head and neck squamous cell carcinoma (HNSCC) tumor progression." (PMID 25005870, 2014).
intestinal cancer (1 paper, 2012). "In the present study, we generated an Hltf deficient mouse allele, and applied this mouse model to characterize the role of loss of HLTF function in the development of intestinal cancer." (PMID 22452792, 2012).
intestinal tumors (1 paper, 2012). "To determine whether the loss of HLTF function could have a role in the progression of intestinal tumors, we introduced the Hltf null mutation into Apcmin/+ mice." (PMID 22452792, 2012).
liver cancer (1 paper, 2023). An epithelial or non-epithelial malignant neoplasm that arises from the liver. "Using data in the TCGA-LIHC database, we analyzed HLTF expression levels via GSEA and found that high HLTF expression was related to the proliferation and metastasis of liver cancer." (PMID 36670110, 2023).
lung squamous cell carcinoma (1 paper, 2018). "In silico analyses identified HLTF gene alterations more frequently in lung squamous cell carcinoma than in adenocarcinoma." (PMID 29661164, 2018).
lymph node metastases (1 paper, 2017). "The multivariate analysis showed that HPP1/TPEP and HLTF along or in combination were independent prognostic factor of worse OS after adjusting for lymph node metastases, distant metastases, age, tumor size." (PMID 28187169, 2017).
Lynch syndrome (1 paper, 2024). An autosomal dominant hereditary neoplastic syndrome characterized by the development of colorectal carcinoma and a high risk of developing endometrial carcinoma, gastric carcinoma, ovarian carcinoma, renal pelvis carcinoma, and small intestinal carcinoma. "The gene ontologies for list 7- linked CHTOP, ADNP, HLTF, WAPL, ZMYM4, and ZNF146 to Lynch Syndrome." (PMID 39480826, 2024). "We propose that ADNP, CHTOP, HLTF, MTF2, WAPL, and ZMYM4 are novel genes in Lynch Syndrome." (PMID 39480826, 2024).
nasopharyngeal carcinoma (1 paper, 2014). A carcinoma arising from the nasopharyngeal epithelium. "UBC13, HLTF, and SHPRH in the TS pathway, RAD51 and BRCA1 in the HR pathway, and FANCD2 in the FA pathway are highly expressed in cisplatin-resistant nasopharyngeal carcinoma (NPC) cells." (PMID 25051366, 2014).
non-small cell lung carcinoma (1 paper, 2024). A group of at least three distinct histological types of lung cancer, including non-small cell squamous cell carcinoma, adenocarcinoma, and large cell carcinoma. "HLTF has been identified as a tumor-suppressive biomarker that is methylated in non-small-cell lung cancer; hypermethylation of HLTF is associated with poor survival." (PMID 38163902, 2024).
papillary carcinoma (1 paper, 2014). A malignant epithelial neoplasm characterized by a papillary growth pattern. "In papillary carcinomas, the HLTF protein was detected in both compartments but with a more pronounced staining at the nuclear periphery." (PMID 25005870, 2014).
Schimke immuno-osseous dysplasia (1 paper, 2021). A multisystem disorder characterized by spondyloepiphyseal dysplasia and disproportionate short stature, facial dysmorphism, T-cell immunodeficiency, and glomerulonephritis with nephrotic syndrome. "Mutations in SMARCAL1 lead to Schimke immuno-osseous dysplasia (SIOD), while HLTF/ZRANB3-deficient cells are vulnerable to replication stress and contribute to tumorigenesis." (PMID 34041245, 2021).